IL6 (interleukin 6)
Diseases named in the same sentence as IL6 in open-access papers (continued):
Sharing a sentence is not in itself a finding about the gene and the disease.
ovarian carcinoma (continued). "We found that Neu5Ac supplementation of culture medium stimulated IL-6 and IL-8 production and rescued the ability of ovarian cancer cells expressing SHMT1 shRNA to grow in an anchorage-independent manner and increased their migratory ability." (PMID 28288142, 2017). "Overexpression of IL-6 has been observed in many cancers, such as endometrial, lung, colorectal, breast and ovarian cancers." (PMID 28859117, 2017). "A recent study of 14 cytokines in the plasma of ovarian cancer patients showed that IL-6 was the only one that was significantly elevated in patients with early stage ovarian cancer relative to benign disease." (PMID 29051715, 2017). "In a previous study, the inhibition of thrombopoietin or IL-6 prevented the development of thrombocytosis in mice and significantly enhanced the therapeutic efficacy of paclitaxel in mouse models of epithelial ovarian cancer." (PMID 28903428, 2017). "Antagonizing IL-6/IL-6R signaling was accepted to have therapeutic activity through inhibition of cytokine network in ovarian cancer cell." (PMID 28821817, 2017). "In ovarian cancer ascites, these mediators include IL-6, TNFα, as well as TLR and EGF receptor ligands." (PMID 28275576, 2017). "A recent study on ovarian cancer indicated that paraneoplastic thrombocytosis is due to the enhancements induced in hepatic thrombopoietin synthesis by tumor-derived IL-6." (PMID 28903428, 2017). "We found that Neu5Ac stimulates the expression of the pro-oncogenic inflammatory cytokines interleukin-6 and -8 (IL-6 and IL-8), which was necessary for ovarian cancer tumor growth." (PMID 28288142, 2017). "These molecules were upregulated on CD8+ T cells by IL-6 and IL-10, present in ovarian carcinoma ascites, as well as by tumor-infiltrating DCs." (PMID 28275576, 2017). "Similar to our results with ovarian cancer cells expressing SHMT1 shRNA, loss of N-acetylneuraminic acid synthetase resulted in reduced levels of IL-6 and IL-8." (PMID 28288142, 2017). "Our results suggest a critical role for IL-6, present in ovarian cancer ascites, in promoting highly functional TNFR2+ Tregs, which are shown to be the only Treg subset capable of suppressing TNFR2+ Teffs in ovarian cancer ascites cultures." (PMID 29163543, 2017). "Collectively, these findings demonstrate that loss of SHMT1 results in decreased expression of the pro-oncogenic inflammatory cytokines IL-6 and IL-8, which in turn results in inhibition of ovarian cancer tumor growth." (PMID 28288142, 2017). "Interleukin-6(IL-6), in particular, has been proposed to be a pivotal cytokine promoting ovarian cancer progression." (PMID 28821817, 2017). "IL-6 secretion by ovarian cancer cells is also increased by platinum-based chemotherapy and promotes the polarization of TAMs toward a protumorigenic and chemoresistant phenotype." (PMID 28275576, 2017). "Both of these studies suggest IL-6 and VEGF as possible diagnostic biomarkers for ovarian cancer with reasonable sensitivities and specificities for clinical applications." (PMID 28487810, 2017). "Accordingly, high IL-6 levels in ascites predicted a shorter PFS in patients with EOC, and the therapeutic potential of targeting IL-6 and downstream signaling has been shown in mouse models of ovarian cancer." (PMID 28388577, 2017). "The omentum is an organ primarily composed of adipocytes, and these cells also can promote homing, migration, and invasion of ovarian cancer cells through release of cytokines such as IL-8 and IL-6." (PMID 28819364, 2017). "To explore the relationship between Tregs, TNF, and IL-6 in ovarian cancer ascites, we created an in vitro system to study the effect of IL-6 and TNF within cell-free ovarian cancer ascites on TNFR2+ Treg and on TNFR2+ Teff frequency and function." (PMID 29163543, 2017). "A profile of cytokines in the ascites of epithelial ovarian cancer patients identified enhanced expression of many factors including angiopoietin, IL-6, IL-8, IL-10 MCP-1, and RANTES." (PMID 27852034, 2016).
ovarian carcinoma (continued). "In ovarian cancer, high levels of IL-6 promote tumor growth, migration, invasion and facilitate chemoresistance and angiogenesis." (PMID 27852034, 2016). "Thirdly, flavonoids are shown to modulate the inflammatory cytokines such as TNF-α and IL-6, which is inseparable with ovarian cancer." (PMID 26960146, 2016). "Downregulation of AXL through the IL6/STAT3 pathway resulted in overcoming taxol resistance in ovarian cancer cells." (PMID 27590506, 2016). "Accumulating evidence suggests a rationale for anti- IL-6/IL-6R therapy for ovarian cancer treatment." (PMID 27825119, 2016). "In agreement with the established function of deregulated STAT3 in ovarian cancer, IL-10, IL-6, and LIF were confirmed as components of the signaling network established by tumor cells and TAMs." (PMID 27215396, 2016). "Among the different LPA receptors, the LPA2 receptor is recognized as the most efficient one that mediates the production of IL-6 and IL-8 in ovarian cancer cells through activation of NF-κB and AP-1." (PMID 27134758, 2016). "We demonstrated that interleukin 6 (IL-6) is enriched in the malignant ascites from patients with ovarian cancer, which enhanced invasive properties of EOC cells." (PMID 27825119, 2016). "IL6 is involved in inflammatory autoimmune diseases and increased levels in a human ovarian cancer line results in anchorage independent growth, proliferation and invasion through Matrigel." (PMID 26512722, 2015). "IL-6 positive cells were also CD-68 positive, suggesting that IL-6 expressing cells surrounding ovarian cancers are mainly macrophages." (PMID 25658637, 2015). "IL-6 has been shown to be a major contributing factor in growth and progression of ovarian cancer, celiac disease and neck squamous cell carcinoma." (PMID 26528857, 2015). "Our study showed that enriched IL-6 secretion from M2-polarized macrophages in ascites promotes ovarian cancer progression through “high” expression of IL-6R in ovarian cancer cells." (PMID 25658637, 2015). "First, we immunostained ovarian cancer tissues including surrounding stroma with anti-IL-6 antibody and found that IL-6 was strongly expressed in stroma, even if cancer cells little expressed IL-6." (PMID 25658637, 2015). "In conclusion, we showed that “high” IL-6R is an independent prognostic factor of ovarian cancer patients and IL-6 from TAMs present in ascites promotes ovarian cancer invasion, proliferation and angiogenesis." (PMID 25658637, 2015). "Release of multiple inflammatory cytokines into the plasma, including IFNγ, IL-1β, IL-6, IL-8, IL-10, TNFα, PlGF, and HSP90B1, is frequently associated with epithelial ovarian cancers (EOC)." (PMID 26858849, 2015). "The data presented herein suggest a rationale for anti-IL-6/IL-6R therapy to suppress the peritoneal spread of ovarian cancer, and represent evidence of the therapeutic potential of anti-IL-6R therapy for ovarian cancer treatment." (PMID 25658637, 2015). "It was shown in in vivo models of EOC that orally administered minocycline was highly effective in decreasing tumor burden and suppressing ovarian cancer-induced malignant ascites by targeting IL-6." (PMID 26282935, 2015). "Since “high” expression of IL-6R but not IL-6 affected the prognoses of patients with ovarian cancer, we quantified the expressions of IL-6 and IL-6R in ovarian cancer cell lines by real-time RT-PCR." (PMID 25658637, 2015). "Ovarian cancer ascites were collected from patients, and we found that primary CD11b+CD14+ cells, which were predominantly M2-polarized macrophages, are the major source of IL-6 production in an ovarian cancer microenvironment." (PMID 25658637, 2015). "In this study, we showed that IL-6 in ovarian cancer ascites is mainly derived from CD11b+CD14+CD206+ cells, M2-polalized macrophages, TAMs." (PMID 25658637, 2015).
ovarian carcinoma (continued). "Next, as several previous reports demonstrated that IL-6 was elevated in the serum as well as peritoneal fluid of patients with ovarian cancer, we focused on the primary cells present in ovarian cancer ascites." (PMID 25658637, 2015). "The data presented herein suggest a rationale for anti-IL-6/IL-6R therapy to suppress the peritoneal spread of ovarian cancer and provide evidence of the therapeutic potential of anti-IL-6R therapy to cure this miserable disease." (PMID 25658637, 2015). "Further elucidation will be needed to clarify the source and role of IL-6 in ovarian cancer microenvironments." (PMID 25658637, 2015). "Recently, plasma levels of IL-6 and thrombopoietin were found to significantly correlate with platelet counts in ovarian cancer patients." (PMID 25469228, 2014). "IL-6 has also been demonstrated to provide paracrine growth stimulation when monocytes are attracted to types of ovarian cancer that produce macrophage colony-stimulating factor." (PMID 24527095, 2014). "We have recently shown enhanced secretion of interleukin-6 (IL-6) and G-CSF and activation of associated downstream STAT3 pathway in several ovarian cancer cell lines in response to cisplatin or paclitaxel treatments in vitro." (PMID 24782986, 2014). "Ovarian cancer cell lines and tumor biopsies have been shown to express elevated levels of IL-6, TNF, CXCL12, and its receptor CXCR4, and expression of these is co-regulated." (PMID 24936477, 2014). "For example, elevated plasma levels of IL-6 and thrombopoietin were reported in ovarian cancer patients." (PMID 25469228, 2014). "IL-6 signaling in ovarian cancer cells regulates tumor cell proliferation, invasion and angiogenesis and IL-8 has also been reported to promote ovarian tumor growth in vivo." (PMID 24527095, 2014). "LPA1 shares this activity with other LPA receptors as LPA3 also mediates both IL6 and IL8 expressions and LPA2 was identified to be the most efficient receptor in linking LPA to IL-6 and IL-8 production in ovarian cancer cells." (PMID 24828490, 2014). "Recent studies have also shown that sustained STAT3 activation is mediated by IL-6 in ovarian carcinoma, cholangiocarcinoma, colon cancer and lung adenocarcinoma." (PMID 25198511, 2014). "Specifically in ovarian cancer, IL-6 enhances tumor cell survival and increases resistance to chemotherapy via JAK/STAT signaling in tumor cells." (PMID 24202339, 2013). "IL6 stimulates inflammatory cytokine production, tumor angiogenesis and the tumor macrophage infiltrate in ovarian cancer and these actions can also be inhibited by a neutralizing anti-IL6 Ab in clinical studies." (PMID 23889749, 2013). "LPA present in the EOC microenvironment was also reported to induce STAT3 phosphorylation and ovarian cancer cell motility through the secretion of IL-6 and IL-8." (PMID 23369187, 2013). "In that scenario, a chimeric antibody against IL-6 is in phase II trials in ovarian cancer treatment." (PMID 23577028, 2013). "In mouse models bearing human ovarian cancer, human IL-6 was found to stimulate hepatocytes via the IL-6 receptor to produce thrombopoietin." (PMID 23864954, 2013). "The concentration of inflammatory cytokines such as IL-1β, IL-6, IL-8, IL-10 was shown to be significantly higher in the ascites of ovarian cancer patients compared to that present in the serum, and correlated with poor prognosis and response to therapy." (PMID 24093089, 2013). "Cytokine inhibitors interrupting the cross-talk between OCCs and MSCs such as IL6 should be investigated as a new therapeutic approach in ovarian cancer." (PMID 23369187, 2013). "Thrombocytosis was significantly correlated with plasma levels of IL-6 in patients with ovarian carcinoma." (PMID 23864954, 2013). "Although IL-6 signaling has been studied extensively in ovarian cancers, several reports have indicated the involvement of many other interleukins in the development of this neoplasm." (PMID 22481932, 2012).
ovarian carcinoma (continued). "In the same study, metastatic and drug-resistant recurrent ovarian tumors expressed significantly higher IL-6 levels than primary ovarian cancer tissue." (PMID 22481932, 2012). "Lysophosphatidic acid (LPA), abundantly released by ovarian cancer cells, is known to contribute to ovarian cancer aggressiveness by stimulating the synthesis of IL-6 and of VEGF, among others." (PMID 22974323, 2012). "For example, IL-6 is elevated in the serum and ascites of patients with ovarian cancer and increased IL-6 concentrations correlate with poor prognoses and chemoresistance." (PMID 23028510, 2012). "A recent study has shown unequivocally that siltuximab (a monoclonal anti-IL-6 antibody) significantly reduced ovarian cancer expression of STAT3 downstream proteins such as Mcl-1, Bcl-X(L), and survivin, implying proapoptotic effects." (PMID 22481932, 2012). "A previous study showed that IL-1β, IL-6 and TGF-β were involved in differentiation and expansion of the Th17 cells in ovarian cancers; IL-1β and IL-6 promoted, whereas TGF-β inhibited, Th17 cell expansion." (PMID 22994684, 2012). "IL-6 stimulates tumour macrophage infiltration in ovarian cancer, and recently it has been shown that this action can be inhibited by the neutralizing anti-IL-6 antibody siltuximab in preclinical and clinical studies." (PMID 22778767, 2012). "The purpose of the present study was to investigate the prognostic significance of IL-6 and IL-8 ascites levels on progression-free survival in a cohort of 39 ovarian cancer patients." (PMID 21619709, 2011). "Although clinical trials of monoclonal antibodies to IL-6 for the treatment of other types of cancer have shown encouraging results, a clear benefit for patients with ovarian cancer remains to be demonstrated." (PMID 21619709, 2011). "IL-6 signaling in ovarian cancer cells can regulate tumor cell proliferation, invasion and angiogenesis IL-8 was recently reported to promote ovarian tumor growth in vivo." (PMID 21619709, 2011). "Specifically, in vivo treatment with IL-6-induced angiogenesis and enhanced endothelial cell-mediated migration of human ovarian carcinoma cells." (PMID 21765834, 2011). "Consequently, further experimental and clinical studies of IL-1 and IL-6 are warranted and may provide a better understanding of interleukin-associated changes to the microenvironment associated with ovarian cancer progression leading to improved prognosis by novel treatment options." (PMID 21765834, 2011). "In conclusion, IL-1 and IL-6 significantly impact the ovarian cancer physiologic and structural microenvironment." (PMID 21765834, 2011). "Although a wide variety of cytokines can be measured in ovarian cancer ascites, interleukin-6 (IL-6) and interleukin-8 (IL-8) are among the most abundant." (PMID 21619709, 2011). "We found that high levels of IL-6 in ascites of newly diagnosed women with ovarian cancer significantly correlated with shorter progression-free survival." (PMID 21619709, 2011). "High levels of interleukin-6 (IL-6), a proinflammatory cytokine and hematopoietic growth factor, are found in both normal ovarian epithelium and human ovarian carcinoma." (PMID 20356397, 2010). "A significant overall correlation between high levels of P-STAT3, EGFR and IL-6 expression has been reported in ovarian cancer specimens." (PMID 19088723, 2009). "The role of cytokines and their receptors is well established in the epithelial cancer microenvironment with IL8 and IL6 known to be involved ovarian cancer pathogenesis." (PMID 18211683, 2008). "Cytokines, such as TNF-α, IL-1, and IL-6, can also induce expression of ST6Gal-I, and interestingly, IL-1 and IL-6 have been shown to increase ovarian carcinoma cell motility and metastasis, as well as being able to up-regulate TNF-α production." (PMID 19014651, 2008). "A synthetic triterpenoid inhibited IL-6-Stat-3 pathway which is one of the key pathway contributing to drug resistance in ovarian cancer." (PMID 19025644, 2008).
ovarian carcinoma (continued). "Recently, correlation between haptoglobin, CA 125 and interleukin-6 have been shown in ovarian cancer." (PMID 15199385, 2004). "Our results demonstrate that circulating IL-6 is mainly derived from the tumour in patients with colorectal, cervical and ovarian cancer." (PMID 12454774, 2002). "Ovarian carcinoma PCF IL-6 activities were correlated with serum C-reactive protein levels (r = 0.65, P = 0.0000, n = 25)." (PMID 10682675, 2000). "As stated, IL‐6/STAT3 plays a vital role in the development of drug‐resistant ovarian cancer." (PMID 40968783, 2026). "High expression of IL‐6 positively correlates with ovarian cancer drug resistance." (PMID 40968783, 2026). "Moreover, in vitro studies have demonstrated that IL‐6 induces chemoresistance in ovarian cancer cells through Ras, Raf, MEK, or ERK‐related signaling pathways." (PMID 40968783, 2026). "Targeting DCLK1 or downstream IL-6/JAK-STAT signaling may therefore offer a rational strategy to disrupt metastatic dissemination in ovarian cancer." (PMID 42210222, 2026). "Overall, IL‐6 can serve as a potential predictor of chemoresistance in ovarian cancer and may assist in identifying its occurrence." (PMID 40968783, 2026). "ALDH1A3, FGF2, and IL-6 have emerged as therapeutic targets for ovarian cancer." (PMID 40507922, 2025). "Recombinant human IL6 (rhuIL6) was used in clinical trials for ovarian cancer patients." (PMID 39766086, 2024). "Resveratrol could counteract the IL6 induction of cell migration in ovarian cancer cells through the induction of autophagy in the cells at the migration front, paralleled by the up-regulation of ARH1 and down-regulation of STAT3 expression." (PMID 39766086, 2024). "In vitro, in vivo, ex vivo and clinical data suggest that platelets promote ovarian cancer progression by activating various signaling pathways including intereleukin-6 (IL-6), nuclear factor kappa B and vascular endothelial growth factor pathways, among others." (PMID 39518024, 2024). "It was found that CCL2 and CCL5 secreted by CAFs could stimulate IL-6 secretion in ovarian cancer cells ultimately resulting in chemoresistance in tumors." (PMID 38932405, 2024). "This suggests that IL-6 might modify the bio-availability of iron in the tumor microenvironment, impacting ovarian cancer development." (PMID 39061859, 2024). "These benefits suggest a potential therapeutic value for IL6 inhibitors in ovarian cancer." (PMID 39766086, 2024). "Functional investigations indicate ovarian cancer progression via the IL-6/STAT3/S100A9 pathway." (PMID 39720595, 2024). "Recent co-culture studies show that cisplatin or carboplatin can promote M2 polarization through the secretion of proinflammatory IL6 from ovarian cancer cells, whereas in other studies, cisplatin was found to promote migration of ovarian cancer cells via M1-like macrophage activity." (PMID 39287565, 2024). "Platelet production in the bone marrow is regulated by paracrine signaling between interleukin-6 and thrombopoietin, which could contribute to increased platelet counts in patients with ovarian cancer." (PMID 39518024, 2024). "All the isolates were evaluated for their ability to inhibit IL-6 activity in the human embryonic kidney-BlueTM IL-6 cell line and their cytotoxic activity against ovarian cancer cell lines (SKOV3/SKOV3-TR) and chemotherapy-resistant variants (cisplatin-resistant A2780/paclitaxel-resistant SKOV3)." (PMID 38998933, 2024). "Resveratrol could counteract the IL6 induction of cell migration in ovarian cancer cells through the induction of autophagy in the cells at the migration front, paralleled by the up-regulation of ARH-I and down-regulation of STAT3 expression." (PMID 39766086, 2024). "Indeed, recent studies have suggested IL6 as a crucial driver in promoting the development and progression of various cancers, including breast, lung, colon, and ovarian cancer." (PMID 39766086, 2024).